TERT (telomerase reverse transcriptase)
Diseases named in the same sentence as TERT in open-access papers (continued):
Sharing a sentence is not in itself a finding about the gene and the disease.
Wilms tumor (3 papers, 2022 to 2025). An embryonal neoplasm characterized by the presence of epithelial, mesenchymal, and blastema components. "Overexpression of the P44L mutant N-MYC (most common MYCN mutation found in Wilms tumor) was associated with increased TERT promoter luciferase activity and TERT expression relative to wild type MYCN." (PMID 35406427, 2022). "TERT transcription is associated with molecular and histologic subgroups in Wilms tumor and telomere-targeted therapies warrant future investigation." (PMID 35406427, 2022). "In contrast to these findings, the present study showed that knockdown of endogenous WT1 in WiT49 human Wilms tumor cells was associated with decreased TERT transcription." (PMID 35406427, 2022). "In the current study, we found an association between MYCN amplification and the P44L MYCN mutation and increased TERT expression in Wilms tumor xenografts and primary tumor specimens." (PMID 35406427, 2022). "In conclusion, this study is the first to report multiple gain-of-function alterations in TERT in Wilms tumor including promoter mutations, promoter hypermethylation, and TERT locus amplification." (PMID 35406427, 2022). "This study found an association between TERT expression/telomerase activity and diffuse anaplasia, the most important prognostic factor in Wilms tumor." (PMID 35406427, 2022). "The present study explored the association between WT1 and TERT because WT1 is mutated in approximately 20% of Wilms tumor specimens and has been previously shown to interact with the TERT promoter." (PMID 35406427, 2022). "Increased TERT mRNA is associated with disease relapse in favorable histology Wilms tumor (WT)." (PMID 35406427, 2022). "To validate the presence of TERT promoter mutations in a separate cohort, we queried the NCI TARGET data for Wilms tumors that underwent whole genome sequencing and found that 3/81 (3.7%) contained the C228T TERT promoter mutation." (PMID 35406427, 2022). "This study then compared the TERT expression in primary Wilms tumors to other pediatric solid tumors using data from the St." (PMID 35406427, 2022). "N-MYC overexpression in Wilms tumor cells resulted in increased TERT promoter activity and TERT transcription." (PMID 35406427, 2022). "This study sought to understand the mechanism of increased TERT expression by determining the association between TERT and WT1 and N-MYC, two proteins important in Wilms tumor pathogenesis that have been shown to regulate TERT expression." (PMID 35406427, 2022). "This study shows that TERT transcription and telomerase activity are upregulated in patient-derived Wilms tumor xenograft specimens with diffuse anaplasia and are positively correlated with the percentage of blastema in WT specimens." (PMID 35406427, 2022). "In contrast, TERT promoter hypermethylation extended beyond specimens with adverse biology and was found throughout the spectrum of Wilms tumor." (PMID 35406427, 2022). "These three TERT promoter mutant primary tumor specimens were found to have significantly increased expression of TERT relative to other tumors in the NCI TARGET Wilms tumor RNA-seq data." (PMID 35406427, 2022). "The current study sought to define molecular and histologic correlates with TERT expression in Wilms tumor." (PMID 35406427, 2022). "This study is novel because it identifies potential mechanisms of TERT activation in Wilms tumor that could be of therapeutic interests." (PMID 35406427, 2022). "This study is novel because it identifies several mechanisms of TERT activation in Wilms tumor that could be of therapeutic interest in the future." (PMID 35406427, 2022). "In summary, this study suggests that N-MYC participates in the TERT regulatory axis, which may govern telomerase function in Wilms tumor and be of therapeutic interest in future studies." (PMID 35406427, 2022). "This study aimed to determine the mechanisms of increased TERT expression in Wilms tumor." (PMID 35406427, 2022).
Wilms tumor (continued). "Overall, these data show that a small proportion of Wilms tumor samples have high TERT expression." (PMID 35406427, 2022). "Therefore, this work provides molecular mechanisms that support the previous observation that increased TERT RNA levels correlate with disease relapse in Wilms tumor." (PMID 35406427, 2022). "The present study hypothesized that WT1 and N-MYC could regulate TERT expression in Wilms tumor because both proteins have been shown to interact with the TERT promoter and both are recurrently mutated or altered in Wilms tumor." (PMID 35406427, 2022). "Next, this study sought to identify the types of TERT alterations in Wilms tumor specimens." (PMID 35406427, 2022). "Therefore, we hypothesized N-MYC regulates TERT in Wilms tumor." (PMID 35406427, 2022). "The previous Children’s Oncology Group analysis of TERT expression and disease relapse was limited to favorable histology, non-anaplastic Wilms tumors." (PMID 35406427, 2022).
alcohol (2 papers, 2017 to 2025). "On the contrary, the HCV and alcohol‐related HCC exhibit a nonproliferation phenotype with moderately‐to‐well differentiation, lower serum AFP levels, and higher CTNNB1 and TERT promoter mutation." (PMID 40948427, 2025).
alcohol abuse (2 papers, 2020 to 2024). The use of alcoholic beverages to excess, either on individual occasions ("binge drinking") or as a regular practice.
anaplastic glioma (2 papers, 2020 to 2022). "In diffuse and anaplastic gliomas that showed TERT promoter mutations were associated with poor survival while 1p/19q co-deletions had a favorable effect." (PMID 34558656, 2022).
Autoimmunity (2 papers, 2018 to 2020). The occurrence of an immune reaction against the organism's own cells or tissues. "In our experience with TERT-immunotherapies we have observed autoimmunity effects marked by a consistent, although transient, B-cell depletion after TERT-specific adoptive T cell transfer in a rodent model but never with a genetic vaccination approach." (PMID 30537967, 2018).
Beckwith-Wiedemann syndrome (2 papers, 2020 to 2023). Beckwith-Wiedemann syndrome (BWS) is a genetic disorder characterized by overgrowth, tumor predisposition and congenital malformations. "TGF-β, together with the tumor suppressor CTCF, epigenetically and/or transcriptionally regulate tumor promoter genes, including IGF2, TERT, and Myc in TGF-β–defective mice and in patients with Beckwith-Wiedemann syndrome (BWS), a human stem cell disorder." (PMID 33457451, 2020).
benign prostatic hyperplasia (2 papers, 2023 to 2025). A non-cancerous nodular enlargement of the prostate gland. "Genome-wide association studies (GWAS) and meta-analyses of candidate gene studies have repeatedly implicated telomerase reverse transcriptase (TERT) variants in benign prostatic hyperplasia (BPH)." (PMID 41379209, 2025).
brain glioma (2 papers, 2020 to 2023). A malignant glioma that involves the brain. "It has been suggested that TERT promoter mutations are associated with a poor survival rate in IDH-wildtype lower-grade brain gliomas." (PMID 32228694, 2020).
cerebrovascular disease (2 papers, 2024). "Previous observational studies have highlighted potential relationships between the telomerase reverse transcriptase (TERT) gene, short leukocyte telomere length (LTL), and cerebrovascular disease." (PMID 39180127, 2024).
cervical dysplasia (2 papers, 2020 to 2025). "TERT is also increasingly expressed in the cascade of cervical dysplasia." (PMID 40025596, 2025). "However, telomerase activity increases in cervical dysplasia due to E6-induced TERT transcription and direct interactions with TERT." (PMID 40025596, 2025).
Chordoid Meningioma (2 papers, 2022 to 2025). A WHO grade II, usually recurring meningioma characterized by the predominance of tissues that are histologically similar to chordoma. "Additionally, due to the scarcity of molecular testing data for this subtype, the overall incidence of TERT mutations in intraspinal chordoid meningiomas remains undefined." (PMID 41013491, 2025). "Chordoid meningiomas were enriched in mutations in chromatin remodeling genes EP400 (8/11,73%) KMT2C (4/11, 36%) and KMT2D (4/11, 36%), and showed low or absent NF2, TERT, SMO, and AKT1 mutations." (PMID 35440040, 2022).
chronic myeloid leukemia (2 papers, 2016 to 2021). "This further led to TERT reduction induced senescence in chronic myeloid leukemia." (PMID 34440361, 2021).
cryptogenic cirrhosis (2 papers, 2012 to 2025). "In the third TERT mutation family (R1254), the father of the proband died of cryptogenic cirrhosis." (PMID 22853774, 2012).
E. coli infection (2 papers, 2022 to 2023). "Similarly, TERT-NHUC uroepithelial cells cultured under normal glucose condition showed a rapid increase of S100A7 mRNA peaking already after 15 min of E. coli infection." (PMID 36127330, 2022). "Likewise, treatment with the COX-2 inhibitor downregulated the AMP psoriasin, encoded by S100A7, in human uroepithelial cells, 5637 and TERT-NHUC during non-infected state and after E. coli infection on both mRNA and protein levels." (PMID 37697284, 2023).
embryonal carcinoma (2 papers, 2021 to 2022). A non-seminomatous malignant germ cell tumor characterized by the presence of large germ cells with abundant cytoplasm resembling epithelial cells, geographic necrosis, high mitotic activity, and pseudoglandular and pseudopapillary structures formation. "In qPCR, TERT was under the limits of detection in normal human dermal fibroblasts (NHDF), hBM-Muse, and hAMSC-SSEA-3(+) cells, while its signal was detectable in pluripotent human embryonal carcinoma (NTERA-2)." (PMID 36241699, 2022).
endometrioid carcinomas (2 papers, 2018 to 2026). "The endometrioid carcinomas were very often TERT hypermethylated whereas the opposite occurred in germ cell tumors, respectively, 83% and 11%." (PMID 29882921, 2018). "As expected, TERT was not methylated in our series of non-epithelial germ cell tumors; on the other hand, TERT is hypermethylated in 83% of endometrioid carcinomas but in only 71% of serous and 50% of mucinous carcinomas." (PMID 29882921, 2018).
endothelial dysfunction (2 papers, 2019 to 2024). In vascular diseases, endothelial dysfunction is a systemic pathological state of the endothelium (the inner lining of blood vessels) and can be broadly defined as an imbalance between vasodilating and vasoconstricting substances produced by (or acting on) the endothelium. "Telomere shortening and senescence have been observed in atherosclerotic areas of human vasculature, and inhibition of human telomerase results in endothelial dysfunction, reversible by TERT expression." (PMID 38475941, 2024). "Our recently published work shows that TERT−/− mice are pre-disposed to endothelial dysfunction induced by Ang II, while TERT overexpressed mice were protected from this effect." (PMID 31001540, 2019).
familial cancers (2 papers, 2022 to 2024). "Some familial cancers, caused by germline mutations in the TERT gene, are referred to as “long telomere syndromes”." (PMID 35892638, 2022).
Fanconi anaemia (2 papers, 2013 to 2017). "We have identified signatures of positive selection acting within regions of the genes directly involved in telomere maintenance in M. lucifugus (DKC1 and TERT) and within the Fanconi anaemia/BRCA pathway DNA repair pathway in naked mole rat." (PMID 24237966, 2013).
gastrointestinal stromal tumor (2 papers, 2015). "A few studies have examined TERT promoter mutations in gastrointestinal stromal tumors (GISTs)." (PMID 26753123, 2015). "However, the contribution of polymorphisms in the TERT and CLPTM1L gene region to gastrointestinal stromal tumors (GISTs) risk is still unknown." (PMID 26372813, 2015).
germ cell tumor (2 papers, 2016 to 2018). A benign or malignant, gonadal or extragonadal neoplasm that originates from germ cells. "GWAS of a testicular germ cell tumor identified two independently associated polymorphisms in the TERT-CLPTM1L locus, rs4635969 and rs2736100." (PMID 26621837, 2016).
gliosarcoma (2 papers, 2021 to 2022). A rare histological variant of glioblastoma (WHO grade IV) characterized by a biphasic tissue pattern with alternating areas displaying glial and mesenchymal differentiation (WHO). "Other mutations seen in high frequency in this particular analysis of gliosarcoma include TERT promoter, CDK2NB, RB1, and STAG2." (PMID 34504233, 2021).
granulosa cell tumor (2 papers, 2023). A slow-growing, malignant tumor, characterize by the presence of granulosa-like cells and Call-Exner bodies, that is almost always found in the ovary.
Hepatitis (2 papers, 2018 to 2025). Inflammation of the liver. "In this study, we investigated the prevalence of TERTp and CTNNB1 exon 3 mutations, as well as TERT gene expression, in HCC, cirrhotic, and hepatitis tissues from Brazilian patients." (PMID 40650279, 2025). "TERT gene expression analysis revealed robust overexpression in HCC tissues compared to cirrhotic and hepatitis tissues (p < 0.001), independent of C228T mutation status." (PMID 40650279, 2025). "TERT promoter mutations were detected in 47.6% of HCC tissues, including C228T (45.2%) and C250T (2.4%), and were also present in 19% of cirrhotic tissues but absent in hepatitis samples, supporting their emergence in early hepatocarcinogenesis." (PMID 40650279, 2025).
hydatidiform mole (2 papers, 2015 to 2022). A gestational trophoblastic disorder characterized by marked enlargement of the chorionic villi, hyperplasia of the villous trophoblastic cells and hydropic changes. "In the DNA from CHM (complete hydatidiform mole, CHM1h-TERT), the OM consensus map showed an allele with the loss of the 45PROX but without the NPHP1 inversion, presenting a potential novel SV haplotype (termed H5)." (PMID 26641089, 2015).
infertile (2 papers, 2020 to 2021). "Consequently, altered telomere-associated gene expression and reduced TERT protein levels in the follicles of aged mice may be a determinant of telomere shortening during ovarian aging, and infertility appearing in the later decades of reproductive lifespan." (PMID 34330985, 2021). "Male TERT-/- zebrafish mutants exhibit a significantly decreased production of mature sperm while TERT-/- females become infertile with age." (PMID 32751994, 2020).
intimal sarcoma (2 papers, 2022 to 2025). A malignant neoplasm arising from the large blood vessels. "Subtype-specific associations included TERT amplification in intimal sarcoma and SWI/SNF complex alterations in uterine adenosarcoma." (PMID 35705560, 2022). "Subtype-specific associations include TERT amplification in intimal sarcoma and SWI/SNF alterations in uterine adenosarcoma." (PMID 35705560, 2022). "Within our cohort, TERT amplification occurs in 44% of intimal sarcomas." (PMID 35705560, 2022).
keratinocyte carcinoma (2 papers, 2020 to 2025). A skin cancer arising from the keratin-producing cells of the epidermis.
kidney tumors (2 papers, 2020 to 2024).
laryngeal squamous cell carcinoma (2 papers, 2022). A squamous cell carcinoma that arises from the larynx. "This is the first study to evaluate the relationship between the Rs2736100 (A>C) polymorphism of the TERT gene and laryngeal squamous cell carcinoma and correlate them with the clinical and pathological characteristics of this pathology." (PMID 36415512, 2022).
leiomyoma (2 papers, 2018 to 2020). A well-circumscribed benign smooth muscle neoplasm characterized by the presence of spindle cells with cigar-shaped nuclei, interlacing fascicles, and a whorled pattern. "Four additional leiomyoma variants in our meta-analysis, one at the TERT locus, two in ATM, and one at the OBFC1 locus, have previously been associated with cancer risk." (PMID 30194396, 2018).
Lewis Lung Carcinoma (2 papers, 2023). "In accordance, TERT deficiency was reported to inhibit vascular development in Lewis Lung Carcinoma xenografts." (PMID 37085672, 2023). "To study the potential role of TERT in the lung tumor microenvironment, we generated NSCLC models by inducing a Lewis Lung Carcinoma (LLC) in wild-type and TERT-deficient mice." (PMID 37085672, 2023). "Using Lewis Lung carcinoma xenograft experiments, Tert−/− mice exhibited reduced tumour growth and micro‐vessel density compared to wild types, highlighting tumour progression and capillarisation relies on TERT." (PMID 37041671, 2023).
lung NETs (2 papers, 2017 to 2025). "Emerging molecular markers, such as protein expression of CD44, ASCL1, and OTP and TERT gene expression have shown prognostic value in lung NETs, alongside traditional markers like Ki-67 and somatostatin receptors." (PMID 40026252, 2025).
lymphoid neoplasm (2 papers, 2016 to 2023). A neoplasm composed of a lymphocytic cell population which is usually malignant (clonal) by molecular genetic and/or immunophenotypic analysis. "In this study, a limited subset of other lymphoid neoplasms were reported to be free of TERT promoter mutations." (PMID 27792139, 2016).
lymphoproliferative disorders (2 papers, 2016 to 2023). "In the light of the possible integration of TERT inhibitors in chemotherapeutic regimens, we treated the LCLs with two drugs used in manage lymphoproliferative disorders (FLU and CY), both alone and in combination with BIBR." (PMID 28032863, 2016).
malignant peripheral nerve sheath tumor (2 papers, 2014 to 2021). Malignant peripheral nerve sheath tumor (MPNST) is a rare and often aggressive soft tissue sarcoma occurring in a wide range of anatomical sites. "In addition, two malignant peripheral nerve sheath tumors (MPNSTs) harbored a TERT promoter mutation (2/35; 6%), one case with a C228T and the other one with a C250T mutation." (PMID 24726063, 2014).